POLD1 (DNA polymerase delta 1, catalytic subunit)
Diseases named in the same sentence as POLD1 in open-access papers (continued):
Sharing a sentence is not in itself a finding about the gene and the disease.
colorectal cancer (continued). "There were eleven breast cancer and six colorectal cancer cases with signature a which did not have any coding POLD1/E or MMR variants." (PMID 32245405, 2020). "Mutations in genes, such as POLD1, CDKN2C, and HIST1H3B, are involved in the pathogenesis of various cancers, such as colorectal cancer, melanoma, and gliomas, but a mutation in these genes may be important for the progression of BRCA." (PMID 31311202, 2019). "However, regarding colorectal cancer, at least 12 known CRC cell lines have been reported to harbor either heterozygous or homozygous mutations in POLD1." (PMID 26755646, 2016). "Similarly, in colorectal cancer, POLD1-mutant tumors demonstrate enhanced responsiveness to ICIs, with an overall response rate of 89% compared to 54% in dMMR/MSI-H tumors (P=0.01), suggesting that PD-L1-mediated immune suppression is a critical evasion strategy that can be targeted therapeutically." (PMID 40661943, 2025). "Hypermutated colorectal cancer with POLE/POLD1 variants may benefit from therapy with immune checkpoint inhibitors (ICIs), providing new treatment opportunities for patients carrying POLE/POLD1 variants." (PMID 37990341, 2023). "As it is widely known that patients with MSI-H tumors can benefit from immunotherapy, routine clinical genetic testing for both POLD1/POLE and MSI-related mutations may help identify patients with endometrial and colorectal cancers who could respond well to immunotherapy." (PMID 36980791, 2023). "The L474P mutation in POLD1 is associated with hereditary nonpolyposis colorectal cancer." (PMID 37175782, 2023). "Moreover, the recent advances in molecular techniques, in particular Next-Generation Sequencing, have led to the identification of many new genes involved in the predisposition to colorectal cancers, such as RPS20, POLE, POLD1, AXIN2, NTHL1, MSH3, RNF43 and GREM1." (PMID 36768460, 2023). "As many of these mutations represent variants of unknown significance, future studies applying suitable syngeneic POLD1 model systems are urgently needed to clarify the functional significance of these genetic changes in colorectal cancer as well as other tumor entities." (PMID 26755646, 2016). "Other emerging biomarkers such as POLE/POLD1 and RET, though still in early validation phases, have expanded stratification and therapeutic approaches for colorectal cancer patients." (PMID 40308511, 2025). "No PV were found in other genes associated with colorectal cancer and/or polyposis, including POLE/POLD1 genes." (PMID 39031223, 2024). "The frequency of variation of POLD1 in lung cancer patients and all cancer patients in this study was significantly higher than that of the COSMIC database, while no such difference was found with colorectal cancer." (PMID 31673068, 2019).
endometrial cancer (36 papers, 2013 to 2026). Primary or metastatic malignant neoplasm involving the endometrium (mucous membrane that lines the endometrial cavity). "Somatic POLE variants have been observed in 2%–8% of CRCs and 7%–15% of endometrial cancers; however, somatic POLD1 variants are extremely rare." (PMID 41214301, 2026). "POLD1- related cases are linked to endometrial cancer, breast cancer, and brain tumors, whereas POLE- related cases are associated with duodenal adenomas and cancer, ovarian cancer, brain tumors, pancreatic cancer, breast cancer, and melanoma." (PMID 41214301, 2026). "Recently, a Japanese family with a POLD1 variant was identified in which the proband had attenuated colorectal polyposis and endometrial cancer." (PMID 41214301, 2026). "The POLD1 mutation rate was 8% in patients with endometrial cancer according to the TCGA PanCancer atlas." (PMID 39910288, 2025). "Loss of SNRPB reduced endometrial cancer cell growth and invasion by regulating the retention of POLD1 introns." (PMID 39910288, 2025). "Conversely, the risk of endometrial cancer by age 70 seems higher in POLD1 (75%) than in POLE (25%)." (PMID 41487566, 2025). "This cohort study explores the prevalence of and outcomes associated with POLE and POLD1 alterations among patients of different races with endometrial cancer (EC)." (PMID 38231514, 2024). "PPAP is caused by heterozygous germline POLE or POLD1 PV and is associated with gastrointestinal polyposis, as well as adult-onset colorectal and endometrial cancer, and other tumor types." (PMID 39031223, 2024). "What is the prevalence of POLE and POLD1 pathogenic alterations and their association with outcomes in patients of different racial groups with endometrial cancer (EC)?" (PMID 38231514, 2024). "Her family history included endometrial cancer, which is in keeping with the POLD1 mutation-related hereditary cancer syndrome spectrum." (PMID 38067377, 2023). "In humans, germline mutations in POLD1 resulting in defective DNA proofreading exonuclease function are associated with hereditary colorectal and endometrial cancer and colonic polyposis." (PMID 38067377, 2023). "When defective, the POLD1 exonuclease domain mutation contributes to increased somatic mutation burdens, a predisposition to hereditary colorectal and endometrial cancer, and colonic polyposis." (PMID 38067377, 2023). "Although POLD1 germline mutation was primarily linked to colorectal and endometrial cancers, more recent data have also found a connection between this mutation and an increased risk of many other tumor types." (PMID 36980791, 2023). "Our conclusion is supported by a separate study which found a POLD1 exonuclease deficiency mutational signature in endometrial cancers with mutations in POLD1’s DEDD motif residues D316 and E318." (PMID 38067377, 2023). "On balance, overexpression of POLD1 p.D402N directly increased mutation counts, SNP, INDEL, and imparted a POLD1 exonuclease deficiency specific mutational signature on the cancer genome in our engineered endometrial cancer cell line model." (PMID 38067377, 2023). "Germline mutations in the DNA polymerase delta 1 (POLD1) exonuclease domain cause DNA proofreading defects, tumor hypermutation, and predispose to hereditary colorectal and endometrial cancer." (PMID 38067377, 2023). "The patient with a POLD1 variant in our cohort had a personal history of endometrial cancer in addition to a family history of CRC and breast cancer." (PMID 35128723, 2022). "Mutation in the POLD1 gene is associated with autosomal dominant predisposition to colonic adenomatous polyps, colon cancer, endometrial cancer (EDMC), breast cancer, and brain tumors." (PMID 35620275, 2022). "POLD1 pathogenic variants have also been found to be linked to an increased susceptibility to endometrial cancer, breast cancer, and possibly brain cancer." (PMID 35128723, 2022).
endometrial cancer (continued). "Compared with POLE, POLD1 mutations are less frequently observed in endometrial cancers, although a few POLD1 mutations have been reported in G3 EC." (PMID 35002543, 2021). "Studies have indicated that tumorous lesions other than colorectal cancer include duodenal adenomas or central nervous system tumors in POLE gene variants and endometrial cancer, breast cancer, and central nervous system tumors in POLD1 gene variants." (PMID 34185173, 2021). "In summary, germline and somatic mutations in the POLE and POLD1 genes appear to predispose to, or promote, colorectal and endometrial cancers in part by increasing the rates of SBSs." (PMID 24705290, 2014). "Taken together, the phenotype suggests the possibility that this POLD1 variant may contribute to the development of endometrial cancer in this family." (PMID 38067377, 2023). "Additionally, the presence of pathogenic POLD1 germline alterations has been linked with some hereditary tumors, such as colorectal and endometrial cancers." (PMID 36980791, 2023). "Mutations in the POLD1 gene have been associated with several genetic disorders, including autosomal dominant inherited forms of neurodegeneration, such as neuroferritinopathy, as well as certain forms of colorectal and endometrial cancers." (PMID 37623222, 2023). "Indeed, when we excluded tumours with MSI-H and tumours containing POLE/POLD1 mutations from the analysis, we found a significant positive association between mutation burden and age in endometrial cancer (adj." (PMID 33879792, 2021). "Interestingly, mutations in POLD1 are—apart from colorectal and endometrial cancer —also associated with a rare human disorder termed mandibular hypoplasia, deafness, progeroid features, and lipodystrophy (MDPL) syndrome." (PMID 31278166, 2019). "Both POLE and POLD1 have been associated with an increased risk of endometrial cancer." (PMID 28331556, 2017). "Our data could have clinical implications regarding tumor genotype-based cancer therapy, as inactivating POLD1 mutations have recently been identified in small subsets of colorectal and endometrial cancers." (PMID 26755646, 2016). "The apparent difference in tumour spectrum between carriers of the POLE p.Leu424Val and the POLD1 p.Ser478Asn substitutions was unexplained and the authors mention that similar differences are found in Lynch syndrome where endometrial cancer seems to be more frequent in carriers of MSH6 mutations." (PMID 24788313, 2014). "Furthermore, POLD1 proofreading (exonuclease) domain mutations were associated with a deficient proofreading repair during DNA replication and an increased incidence of epithelial cancers, especially colorectal and endometrial cancer." (PMID 35189839, 2022). "Currently ongoing whole-genome sequencing studies are expected to additionally determine the POLD1 mutation rates in tumor entities other than CRC or endometrial cancer, which could then broaden the applicability of the here proposed concept of a novel tumor genotype-based anti-cancer therapy." (PMID 26755646, 2016). "Intron retention decreases the expression and normal function of the canonical POLD1 gene post-transcriptionally in endometrial cancer cells." (PMID 39910288, 2025). "Endometrial cancer cells were tested for their metastatic capacity via Transwell assays in which POLD1 was silenced, and the results demonstrated that POLD1 depletion inhibited the migratory and invasive capacities of Ishikawa, AN3CA and HEC-1A cells." (PMID 39910288, 2025). "The ratio of patients with high POLD1 mRNA expression was 8%, and high POLD1 expression was associated with worse Progression Free Survival (PFS) in patients with endometrial cancer." (PMID 39910288, 2025). "While colorectal and endometrial cancers are the most frequent manifestations, the full tumor spectrum of POLD1-related PPAP remains incompletely defined." (PMID 41487566, 2025).
endometrial cancer (continued). "SNRPB depletion increased the proportion of intron 22 retention in POLD1 in endometrial cancer cells." (PMID 39910288, 2025). "SNRPB promoted the malignant progression of endometrial cancer cells through regulating POLD1 expression." (PMID 39910288, 2025). "Differential expression of POLD1 was detected via qPCR and western blotting in freshly frozen endometrial cancer and normal endometrial tissues, which revealed that POLD1 was significantly highly expressed in endometrial cancer." (PMID 39910288, 2025). "We interrogated the TCGA PanCancer atlas database to determine POLD1 mRNA expression in patients with endometrial cancer." (PMID 39910288, 2025). "The correlation between POLD1 mRNA expression and clinical outcomes was examined via the Kaplan–Meier plot website, and high POLD1 expression was also correlated with poor OS and relapse-free survival in patients with endometrial cancer." (PMID 39910288, 2025). "In this study, we find that silencing the expression of the splicing factor SNRPB decreased POLD1 expression levels in endometrial cancer cells, and POLD1 was identified as a critical downstream target of SNRPB in endometrial cancer cells." (PMID 39910288, 2025). "Overall, SNRPB promotes the efficient splicing of POLD1 by regulating intron retention, ultimately contributing to high POLD1 expression in endometrial cancer." (PMID 39910288, 2025). "Affected carriers developed colorectal and endometrial cancers, but also duodenal adenocarcinomas: this is the first report of this tumor type in germline POLD1 carriers." (PMID 41487566, 2025). "To investigate the role of POLD1 in endometrial cancer cells, we used siRNA to deplete POLD1 in Ishikawa, AN3CA and HEC-1A cells." (PMID 39910288, 2025). "SNRPB was significantly positively correlated with POLD1 expression in endometrial cancer (Pearson r = 0.8801)." (PMID 39910288, 2025). "Primers were designed for intron 22 to examine the expression of unspliced intron 22 of the POLD1 transcript (abnormal splicing transcript POLD1-S) after SNRPB depletion in endometrial cancer cells." (PMID 39910288, 2025). "In this study, we reveal that POLD1 intron 22 retention was induced after SNRPB depletion in endometrial cancer cells." (PMID 39910288, 2025). "Our index patient, a germline carrier of POLD1 p.D402N, developed endometrial cancer at a young age." (PMID 38067377, 2023). "POLD1 has been studied in hereditary colon cancer and endometrial cancer, but it has yet to be investigated in glioblastoma." (PMID 36732815, 2023). "The additional cases that were found were associated with colorectal and endometrial cancers, which are disease-specific for POLE/POLD1 exonuclease deficiency associated tumors." (PMID 38067377, 2023). "In the current study, we used HEC1A, an endometrial cancer cell line, as a physiologically pertinent model system to study POLD1 p.D402N function." (PMID 38067377, 2023). "The SBS20 mutational signature is etiologically associated with concurrent POLD1 exonuclease mutation and defective MMR deficiency and was previously identified in endometrial cancer with this co-deficiency." (PMID 38067377, 2023). "It has been recommended that patients with POLD1 and POLE variants undergo regular colonoscopic and gastroscopic surveillance, in addition to screening for endometrial cancer." (PMID 35128723, 2022). "Missense germline mutations in the exonuclease domain of POLD1 were associated with colorectal multiple polyposis and CRC predisposition, as well as for endometrial cancer." (PMID 33672345, 2021). "We showed that mutations in POLE (OR = 0.9690, 95% CI = 0.9422–0.9959, p value = 0.0243) and POLD1 (OR = 0.9573, 95% CI = 0.9223–0.9925, p value = 0.0177) were both more prevalent in younger endometrial cancer patients." (PMID 33879792, 2021).
endometrial cancer (continued). "Both POLE and POLD1 have been associated with an increased risk of endometrial cancer and furthermore POLD1 has been associated with breast and brain tumors in addition to CRC and endometrial cancer." (PMID 32258104, 2020). "We also evaluated the effect of POLD1 mutation on patient survival and found that POLD1 mutation was positively correlated with Progression Free Survival (PFS), Disease Specific Survival (DSS) and OS in patients with endometrial cancer." (PMID 39910288, 2025). "In addition, POLD1 depletion decreased the increase in the malignancy of endometrial cancer cells overexpressing SNRPB." (PMID 39910288, 2025). "The results suggested that SNRPB inhibition decreased POLD1 expression in endometrial cancer cells." (PMID 39910288, 2025). "The germline POLE/POLD1 genetic testing should be considered in the context of a strong family history of colorectal or endometrial cancer (two or more relatives) or a single relative with colorectal cancer or endometrial cancer <60 years." (PMID 40936703, 2025). "Despite multiple reports of germline POLD1 variants involving changes in the DEDD motif in both colorectal and endometrial cancer patients, this mutation class is still classified as VUSs by laboratory submitters in the ClinVar database, rendering these variants clinically inactionable." (PMID 38067377, 2023). "POLD1 has been associated with breast and brain tumours in addition to CRC and endometrial cancer." (PMID 28331556, 2017). "In addition, recently described POLD1 missense mutations predispose to CRC (p.Ser478Asn, p.Pro327Arg), endometrial cancer (p.Ser478Asn) and likely to brain (p.Ser478Asn) and kidney tumors (p.Val392Met)." (PMID 26755646, 2016). "Therefore, POLD1 was selected as an important downstream target of SNRPB in endometrial cancer." (PMID 39910288, 2025). "Hence, POLD1 might play a crucial role as the downstream target responsible for facilitating the oncogenic functions of SNRPB in endometrial cancer cells." (PMID 39910288, 2025). "The study from Haraldsdottir supported the hypothesis of the coexistence of somatic MMR alterations with somatic mutations in DNA polymerase POLE or POLD1 in patients with hypermutated colon and endometrial cancers without germline MMR mutations." (PMID 32258104, 2020). "In the respective endometrial carcinoma TCGA PanCancer Atlas study, which included 509 cases with complete mutations and copy number alterations information, among the 27 cases with CTCFL mutations 22 had mutations in one of the four MSI associated genes or the POLE or POLD1 genes." (PMID 30275357, 2018). "Here, we propose a potential new strategy for controlling the interaction between POLD1 and PCNA through the splicing factor SNRPB in endometrial cancer cells." (PMID 39910288, 2025). "Furthermore, according to data from literature, tumor analysis in a patient with endometrial cancer carrying this germline variant showed a TMB-high phenotype (141 Mut/Mb), an SBS10d mutational signature, a pMMR status and loss of heterozygosity (LOH) at POLD1 (PP4_Strong)." (PMID 41487566, 2025). "Mechanistically, we revealed that SNRPB knockdown decreased POLD1 expression and that POLD1 intron 22 was retained after SNRPB silencing in endometrial cancer cells, as determined via RNA sequencing data analysis." (PMID 39910288, 2025). "Herein, we demonstrated that knockdown of PGK1 inhibited the expression of c-JUN, FOSL1, and POLD1, indicating that PGK1 regulates chemoresistance in endometrial carcinoma through upregulation of DNA repair-related proteins." (PMID 30925862, 2019).
endometrial cancer (continued). "Therefore, the negative correlation between age and mutation loads in endometrial cancer could be explained by the presence of hypermutated tumours in younger patients, which are associated with MSI-H and POLE/POLD1 mutations." (PMID 33879792, 2021).